MX2 (MX dynamin like GTPase 2)
Diseases named in the same sentence as MX2 in open-access papers (continued):
Sharing a sentence is not in itself a finding about the gene and the disease.
HIV-1 infection (continued). "MX2 antiviral activity is also affected by CypA, a ubiquitous and abundantly expressed member of a family of peptidyl-prolyl isomerases, whose role in HIV-1 infection is enigmatic." (PMID 30084827, 2018). "The MX2-mediated block to HIV-1 infection occurs after reverse transcription, but prior to the nuclear import of pre-integration viral nucleoprotein replication complexes." (PMID 30496303, 2018). "Myxovirus resistance protein 2 (Mx2) is an interferon induced inhibitor of HIV-1 infection that prevents capsid-dependent nuclear import of subviral complexes in the late stage during infection." (PMID 29337866, 2018). "Overall, manipulations of NUP155 and other Nup93 subcomplex components recapitulated, abolished, or otherwise modified several of the key cell-type- and CA-dependent differences in the effects of CypA and MX2 on HIV-1 infection." (PMID 30084827, 2018). "Such a model would provide an explanatory basis for the observation that MX2 can enhance or rescue HIV-1 infection in some instances." (PMID 30084827, 2018). "Subsequent investigations revealed that MX2 participates in blocking HIV-1 infection after reverse transcription." (PMID 29379496, 2017). "Overexpression of the type I IFN-induced protein MX2 blocks HIV-1 infection in a CA-sensitive manner, and CA amino acid substitutions N74D or P90A reduce the sensitivity of HIV-1 to ectopic MX2-mediated repression." (PMID 27279606, 2016). "In the current study, we investigated the importance of oligomerization for the antiviral activity of MX2, a closely related family member and potent inhibitor of HIV-1 infection (3, –, 5)." (PMID 26446602, 2016). "Human myxovirus resistance 2 (MX2/MXB) recently has been identified as an interferon-inducible late postentry inhibitor of human immunodeficiency virus type 1 (HIV-1) infection (3, –, 5)." (PMID 26446602, 2016). "Here, we performed site-directed mutagenesis studies to investigate in detail the importance of oligomerization for the inhibition of HIV-1 infection in the context of both human MX2 and the MX1(NMX2) chimera." (PMID 26446602, 2016). "Recently, cultured cell experiments identified human MX2 as a key effector in the interferon-mediated postentry block to HIV-1 infection." (PMID 26446602, 2016). "The human myxovirus-resistance protein B (MxB, also called Mx2) was recently reported to inhibit HIV-1 infection by impeding the nuclear import and integration of viral DNA." (PMID 25571928, 2015). "In sum, the amino terminus of MX2 is sufficient to inhibit HIV-1 infection, provided that it is contained within a protein that can oligomerize, at least into dimers." (PMID 25673704, 2015). "MX2 has recently been reported to be an IFN-induced inhibitor of HIV-1 infection in human monocytoid cell lines." (PMID 25170834, 2014). "Next, we took advantage of MX2, a host restriction factor inhibiting HIV-1 core translocation into the nucleus, to explore the underlying molecular mechanism responsible for GJB2 inhibition of HIV-1 infection." (PMID 40980890, 2025). "In summary, this report demonstrates a specific role for the Cyp domain of RANBP2 in HIV infection and MX2 sensitivity and further indicates that precise manipulation of NPCs is key to revealing the functional interactions that determine the outcome of HIV-1 infection." (PMID 39853118, 2025). "To examine the potential role of CA-independent effects of RANBP2-Cyp on HIV-1 infection and MX2 activity, we next generated cells expressing RANBP2 from its endogenous locus but with specific point mutations introduced into the Cyp domain to alter CA-binding specificity." (PMID 39853118, 2025). "Interestingly, the interferon-induced protein MX2 has been demonstrated to be a crucial effector in interferon-mediated resistance against HIV-1 infection (8, –, 10)." (PMID 39240132, 2024).
HIV-1 infection (continued). "Collectively, these data demonstrate that the effect of CsA on HIV-1 infection and MX2 sensitivity are the direct result of abrogating CA-CypA interactions and do not involve other cyclophilins, and further suggests that they do not involve other cellular functions of CypA." (PMID 38512975, 2024). "HIV-1 infection is known to be markedly mitigated by MX2/MxB." (PMID 37784164, 2023). "MX2 also prevents the uncoating of the viral capsid, leading to the abrogation of HIV-1 infection." (PMID 34394123, 2021). "Deletion of the N-terminal 25 amino acids eliminates the ability of MX2 to block HIV-1 infection." (PMID 32934084, 2020). "In this work, we revisit the importance of the MX2 G domain for the control of HIV-1 infection." (PMID 31722207, 2019). "Interestingly, human population genetic analyses identified that the ancestral allele of Mx2 protects from HIV-1 infection and is associated with lower in vitro HIV-1 replication and increased Mx2 expression in response to IFN-α." (PMID 31426525, 2019). "Notably, knock-down of NUP214, NUP62 or NUP98 had minimal effects (<2-fold) on HIV-1 infection in control cells, indicating that each of these nucleoporins promote MX2 anti-viral function." (PMID 30496303, 2018). "Nevertheless, we could clearly demonstrate circumstances in which manipulating Nup levels (and presumably NPC composition) affected HIV-1 infection and MX2 activity." (PMID 30084827, 2018). "These experiments demonstrate that MX2 and CypA can either inhibit or enhance HIV-1 infection." (PMID 30084827, 2018). "Effects of NUP88 and NUP214 depletion on HIV-1 infection and MX2 activity were generally similar." (PMID 30084827, 2018). "Moreover, there was significant overlap in the identity of Nups and NTRs that mediate MX2 and CypA effects on HIV-1 infection." (PMID 30084827, 2018). "For these reasons and because the nuclear envelope fragments during cell division, we next considered whether the varied effects of CA sequence, MX2, CypA, cell-type and cell-cycle on HIV-1 infection might be mediated through Nups or NTRs." (PMID 30084827, 2018). "Herein, we employed a panel of HIV-1 CA mutants, inhibitors of cell cycle progression and CypA:CA interactions, along with a systematic knock-down of Nups and NTRs to comprehensively investigate the functional interplay between Nups, MX2, CypA, and the viral capsid during HIV-1 infection." (PMID 30084827, 2018). "Moreover, MX2 localizes to nuclear pores and appears to act at the nuclear entry step of HIV-1 infection." (PMID 30084827, 2018). "Our results are in good general agreement with their findings that depletion of NUP214 or TNPO1 impair MX2 anti-viral function in HeLa cells, and also with the apparently variable nucleoporin requirements for HIV-1 infection and MX2 activity among different cell lines." (PMID 30496303, 2018). "The ability of these MX2 stalk mutants to inhibit HIV-1 infection was tested." (PMID 26446602, 2016). "The precise mechanism of MX2 inhibition of HIV-1 infection is currently unknown." (PMID 35880880, 2022). "Each of these possible sources of variation in NPCs could contribute to inconsistency between Nup requirements for HIV-1 infection and MX2 activity between cell lines and could underlie the increased antiviral activity of MX2 in some non-dividing cells." (PMID 30084827, 2018). "Though this could be accomplished by MX2 competitively impeding CA-nucleoporin interactions, we favor the idea that MX2 inhibits HIV-1 infection through a specific process that targets viral replication complexes, a view that is supported by the noted ability of CA mutants to evade MX2." (PMID 30496303, 2018). "Although RANBP2/NUP358 has been repeatedly identified as a critical player in HIV-1 nuclear import and MX2 activity, the mechanism by which RANBP2 facilitates HIV-1 infection is not well understood." (PMID 39853118, 2025). "MX2 and GJB2 consistently inhibited HIV-1 infection, and this was statistically significant for GJB2." (PMID 40980890, 2025).
HIV-1 infection (continued). "On the other hand, HIV-1 infection triggers the over-expression of several RFs genes, including IFITM1, IFITM2, IFITM3, MX1, MX2, TETHERIN, IFN1a, and IFNR." (PMID 39476027, 2024). "During HIV-1 infection, SAMHD1 recognizes the incoming HIV-1 core and sequesters viral components onto MX2-formed molecular traps." (PMID 39240132, 2024). "The MX2 protein has a critical role in antiviral responses; it is induced by interferon-alpha (INF-α) and exhibits potent activity against HIV-1 infection." (PMID 39051372, 2024). "Therefore, to address whether there are capsid-independent effects of CypA on HIV-1 infection or MX2 activity, we generated CypA knock-out cell lines as well as cells expressing CypA from its endogenous locus but with specific point mutations introduced to alter CA-binding specificity." (PMID 38512975, 2024). "Compared to our findings, IRF7, TRIM25, and MX2 were the ‘common ISGs’ that exhibited anti-HIV-1 effects in MT-4 cells and were upregulated by HIV-1 infection." (PMID 30915053, 2019). "Human myxovirus resistance 2 (MX2/MXB) is an interferon-stimulated gene (ISG) and was recently identified as a late postentry suppressor of human immunodeficiency virus type 1 (HIV-1) infection, inhibiting the nuclear accumulation of viral cDNAs." (PMID 26446602, 2016). "As controls, we used parental THP-1 cells, as well as the CRISPR/Cas9 control (Cntrl) cells, which had similar permissivity to HIV-1 infection and expressed comparable MX1 and MX2 levels after IFN-α stimulation." (PMID 27279606, 2016). "Here, we performed structure-function studies to investigate the requirements for oligomerization of both MX2 and chimeric MX1(NMX2) for the inhibition of HIV-1 infection." (PMID 26446602, 2016). "We found that after IFN-α pretreatment and wild-type HIV-1 infection, 2-LTR circles were reduced in parental THP-1 cells ∼30-fold, and only ~10-fold in MX2g2-4 cells, corroborating the role for MX2 in blocking nuclear import." (PMID 27279606, 2016). "MX2 blocks HIV-1 after reverse transcription at the level of nuclear entry, suggesting that IFN-induced host cell barriers are likely to interfere with HIV-1 infection at multiple early steps." (PMID 27279606, 2016). "Finally, HIV-1 infection was significantly reduced in cells expressing the CPSF6 chimeras with NP and MX2 NLSs, despite these NLSs conferring effective CPSF6-358 nuclear localization." (PMID 39823525, 2025). "Finally, HIV-1 infection was significantly reduced in cells expressing the CSPF6 chimeras with NP and MX2 NLSs, despite these NLSs conferring effective CPSF6–358 nuclear localization." (PMID 38979149, 2024). "In the absence of functional CypA (CsA-treated U937 cells), SAMHD1/MX2 still inhibited HIV-1 infection." (PMID 38888311, 2024). "One possibility explaining the ability of T151A/D mutants of MX2 to inhibit HIV-1 infection in the absence of CA-CypA interactions is that the lack of GTP hydrolysis facilitates interactions between the viral CA and the CA-binding site of the GTPase domain." (PMID 38512975, 2024). "MX2 or MXB, another IFNα-induced ISG reduces nuclear accumulation of viral DNA in the nucleus of infected host cells without affecting the reverse transcription indicating its antiviral role at early stages of HIV-1 infection." (PMID 34394123, 2021). "Surprisingly, however, both at the eclipse phase of infection as well as during late-stage chronic infection, HIV-1 infection suppressed baseline levels of IFI44 and showed similar trends with SAMHD1 and MX2 expression, indicating that HIV-1 actively shapes its environment." (PMID 30867315, 2019). "Moreover, certain ‘common ISGs’ that were upregulated by HIV-1 infection (IRF7, TRIM25, MYD88, MX2, LGALS9, and SP100) exhibited a strong anti-HIV-1 effect in THP-1 cells." (PMID 30915053, 2019).
HIV-1 infection (continued). "We observe very similar elevations of MX1; however, MX1, in contrast to MX2, has not been shown to restrict HIV-1 infection, and a comparative analysis in humanized mice has not been previously performed." (PMID 30867315, 2019). "To gain further insight into this issue, we performed spreading HIV-1 infection experiments in the presence of MX2, MX2 (GMX1), or MX1 (as negative control) alone or together with the short isoform of MX2." (PMID 31722207, 2019). "That manipulation of the Nup62 complex had both positive and negative effects on MX2 activity against HIV-1, without affecting MX2 localization, suggests that it participates in HIV-1 infection." (PMID 30084827, 2018). "In cells treated with the non-targeting siRNA, MX2 exhibited an ~8-fold inhibition of HIV-1 infection." (PMID 30496303, 2018). "For this reason, and because MX2 inhibits HIV-1 infection more potently in non-dividing cells, current models suggest that MX2 acts by preventing nuclear import of the viral preintegration complex." (PMID 30084827, 2018). "Overall, the positive and negative effects of CypA and MX2 on HIV-1 infection were clearly dependent on Nups." (PMID 30084827, 2018). "IFN-γ can induce a divergent antiviral state from type I IFNs, and potent IFN-γ-induced early block(s) to HIV-1 infection can be entirely independent of Mx2." (PMID 28100611, 2017). "Since MX2 overexpression reduces the levels of nuclear viral DNA (e.g., 2-LTR circles) and more efficiently suppresses HIV-1 infection in non-dividing cells when compared with dividing cells, MX2 presumably inhibits nuclear import of the viral complex." (PMID 29379496, 2017). "In agreement with previous studies, wild-type human MX2 inhibited HIV-1 infection by ∼90% relative to that of the CD8 negative control, whereas the sole expression of the MX226–715 short isoform had no antiviral effect (upper)." (PMID 26446602, 2016). "In any event, the nuclear envelope location does not appear to be crucial for MxB inhibition of HIV-1 infection, since certain MxB mutants, such as the MxBΔ1-25 + NLS mutant and MX2(N91)-ARFAPTIN 2 mutant, lost localization to the nuclear envelope, yet still exhibited strong anti-HIV-1 activity." (PMID 34093497, 2021). "The mechanism by which MX2 blocks HIV-1 infection in human cells has not been fully resolved, but the block maps to postentry events in the viral life cycle that culminate in integration, and the restriction appears to depend on CypA binding of the viral capsid core (40, –, 42, 63, 66, –, 68)." (PMID 32934084, 2020). "However, our experiments in U87-MG cells indicated that there is no specific requirement for particular nucleoporins for HIV-1 infection, implying effective functional redundancy between multiple nuclear import factors/pathways in MX2’s absence." (PMID 30496303, 2018). "In addition, this MX2-independent IFN-α-induced postentry block can be relieved by pharmacological inhibition of cyclophilins, suggesting a role of host cell cyclophilins in the early type I IFN-induced suppression of HIV-1 infection." (PMID 27279606, 2016). "Importantly, we did not observe clone-dependent effects on HIV-1 infection or MX2 activity." (PMID 38512975, 2024). "Moreover, some Nup depletions (SEH1, NUP85, NUP160, SEC13, NUP98, NUP107, ELYS/ACHTF1, NUP93, NUP205, NUP88, and NUP214) that reduced both HIV-1 infection and MX2 activity in dividing HeLa cells, affected MX2 activity but not HIV-1 infection in non-dividing HeLa cells." (PMID 30084827, 2018). "Thus, IFN-γ can confer potent early protection against HIV-1 infection that is independent of Mx2." (PMID 28100611, 2017). "In line with previous experiments that utilized MX2 as a model system, some NLSs failed to complement the nuclear localization defect of CPSF6-358, and as a result these chimeric proteins restricted HIV-1 infection in the cytoplasm." (PMID 39823525, 2025).
HIV-1 infection (continued). "The T151A mutant of MX2, which binds, but does not hydrolyze GTP, restricted HIV-1 infection in both HeLa and HT1080 cells, confirming that GTPase activity is dispensable for anti-HIV-1 activity." (PMID 38512975, 2024). "We recently reported that during chronic, untreated HIV-1 infection, IFN-I inducible antiretroviral genes APOBEC3G, BST2 and MX2, as well as IFNβ, but not IFNα, were expressed to significantly higher levels when compared to HIV-1 uninfected individuals." (PMID 33064743, 2020). "Since both isoforms of MX2 are IFN inducible, we tested the ability of the short isoform to inhibit HIV-1 infection when ectopically expressed in the absence of IFNα or in its presence (i.e., when both endogenous isoforms are expressed)." (PMID 31722207, 2019). "Unexpectedly, despite efficient Mx2 expression, IFN-α2 did not protect THP-1 cells from HIV-1 infection unless the HIV-1 virus-like particles (VLPs) were decorated with a VSV-G envelope." (PMID 28100611, 2017). "Notably, although the ability of MX2 to restrict HIV-1 infection is reduced in CypA−/− and RANBP2∆Cyp cells, we found that the effect of MX2 on integration targeting was maintained in the absence of CA-Cyp interactions." (PMID 39853118, 2025). "Thus, increased MX2 expression after IFNα treatment had a limited effect on HIV-1 infection in the U937 cells lacking SAMHD1, but in the SAMHD1-expressing U937 cells, IFNα treatment both increased MX2 expression and promoted HIV-1 suppression." (PMID 38888311, 2024). "Thus, while CA-CypA interactions are required for the full antiviral activity of WT MX2, MX2 which can bind but not hydrolyze GTP restricts HIV-1 infection even in the absence of CypA binding." (PMID 38512975, 2024). "However, the inherent dependence of HIV-1 infection upon NUP358, NUP153 and TNPO3 in HeLa cells confounds this analysis since their depletion results in less efficient infection regardless of MX2 expression." (PMID 30496303, 2018). "The canine MX2 ortholog does not inhibit HIV-1, but replacement of the amino-terminal 29 amino acids of the canine protein with those from the human counterpart creates a chimeric protein as effective as human MX2 in suppressing HIV-1 infection." (PMID 25673704, 2015). "While the cell lines used herein are not the natural targets of HIV-1 infection, our results suggest that the in vivo utilization of Nups by HIV-1 and MX2 could vary among cell types (e.g. T cells vs. macrophages or naïve vs. memory vs. effector CD4+ T cells)." (PMID 30084827, 2018).